CDK4 (cyclin dependent kinase 4)
Diseases named in the same sentence as CDK4 in open-access papers (continued):
Sharing a sentence is not in itself a finding about the gene and the disease.
lung cancer (continued). "Transcriptomic alterations that occur during lung cancer development include over-expressed cell cycle related genes like E2F3, BUB3, CDK4, MCM2, MCM3, and MCM7 as summarized by Powell and Borczuk." (PMID 26930711, 2016). "Catechol attenuated the expression of CDK2 and CDK4 and their respective regulatory partners, cyclin E and cyclin D1 in a dose-dependent manner in KP2 and H460 lung cancer cells." (PMID 27167001, 2016). "The method was applied to the A549 lung cancer cell line, and we identified specific kinases known to have an important role in this type of cancer (TGFBR2, EGFR, PHKG1 and CDK4)." (PMID 24961498, 2014). "Knockdown of ATDC reduced the protein levels of cyclin D1, p-Rb, CDK4, CDK6 and c-Myc in the 2 lung cancer cell lines with endogenous expression of ATDC." (PMID 23776433, 2013). "To investigate the mechanism of cell cycle progression regulated by ATDC in lung cancer, we examined the effect of ATDC on cyclin A, cyclin D1, cyclin E, CDK2, CDK4, CDK6, p-Rb and c-Myc in lung cancer cell lines." (PMID 23776433, 2013). "Furthermore, the combined application of miR-506 and miR-143 in the treatment of lung cancer LC and PC synergistically downregulates CDK1, CDK4, and CDK6, blocking both the G1/S and G2/M transitions and inducing robust apoptotic activity." (PMID 40248198, 2025). "Furthermore, the up-regulation of the p21WAF1/CIP1 protein expression was observed along with the down-regulated expression of the CDK family of proteins (CDK4 and CDK6) in both lung cancer cells." (PMID 40941018, 2025). "Moreover, we found that lung cancer and sarcoma (SARC) patients with high CDK4 expression have lower overall survival (OS) rate than those with low CDK4 expression by searching the Kaplan-Meier Plotter database." (PMID 37833461, 2023). "Our study partly illustrated the potential mechanism of CDK4/6 inhibition by QKI‐5, and supported the theory that inhibiting CDK4/6 might be a potential therapeutic method for lung cancer." (PMID 36172919, 2023). "Likewise, baicalein caused cell cycle arrest in G1/S by inhibiting the Akt/mTOR pathway in H1299 and H1650 lung cancer cells, which decreased the expression of the proteins CDK2, CDK4, and cyclin E2." (PMID 37298837, 2023). "Likewise, tetracenomycinsare, an antibiotic produced by the Streptomyces and Nocardia species, induced cell cycle arrest in the lung cancer cells by decreasing the expression levels of cyclin D1 and CDK4 (cyclin-dependent kinase 4)." (PMID 38067602, 2023). "In similar with gilteritinib, quizartinib improved the anti-cancer effect of abemaciclib in lung cancer cells, indicating that FLT3 might confer synthetic lethality to CDK4/6 inhibition." (PMID 35814226, 2022). "Yu and colleagues elucidated that enriching circHIPK3 facilitated the expression of sphingosine kinase 1 (SphK1), cyclin-dependent kinase 4 (CDK4), and signal transducer and activator of transcription 3 (STAT3) through impeding miR-124 in lung cancer cells, and accelerating LC cell growth." (PMID 36292157, 2022). "As a result, abemaciclib, rather than other CDK4/6 inhibitors (ribociclib, palbociclib), synergized with gilteritinib to inhibit the growth of lung cancer cells." (PMID 35814226, 2022). "Of note, the use of CDK4/6 inhibitors in combination with mitogen-activated extracellular signal-regulated kinase (MEK), or mammalian target of rapamycin (mTOR) inhibitors for treating lung cancer are being tested in clinical trials (NCT03170206, NCT02857270)." (PMID 35814226, 2022). "Considering that the cell cycle from G1 to S phase was dramatically promoted in lung cancer cells with decreased FAM117A expression, we next checked whether this can be restrained by CDK4/6 inhibition." (PMID 35280504, 2022).
lung cancer (continued). "In lung cancers, CDK2 levels were over-expressed in more than 90%, and CDK4/6 in more than 23% of the patient samples Therefore, a CDK 2/4/6 triple inhibitor will likely be more effective than CDK4/6 dual inhibitor in these cancers." (PMID 33579185, 2021). "An additional number of microRNAs (miR-124a, miR9, miR200b and miR-106b) were shown to mediate cellular response to CDK4/6 inhibitors in acute lymphoblastic leukemia, breast and lung cancer cells, without, however, affecting sensitivity to treatment." (PMID 34439268, 2021). "Cyclin-dependent kinase 4 (CDK4),a master regulator of the cell cycle belonging to theCDK family, is identified as a major oncogenicdriver among the cell cycle components; also,CDK4 has been found in several tumor types includingbreast and lung cancers." (PMID 31606975, 2020). "Indeed, we observed KLF8 regulated the expression of CDK4 and P21 depending upon JMJD2A, which also contributed to the functions of KLF8 in regulating cell cycle and growth of lung cancer cells." (PMID 31624471, 2019). "Further, we saw enhanced growth suppression in multiple breast and lung cancer cell lines treated with XAV and Palbociclib, demonstrating a consistent combinatorial effect of TNKS and CDK4 blockade across a broad spectrum of cancer cell lines of epithelial origins." (PMID 31891587, 2019). "CDK4 mRNA was highly expressed in lung cancer tissues as a whole but not significantly during different stages." (PMID 31199581, 2019). "Combinations of CDK4/6 and MEK inhibitors have also been shown to be synergistic in preclinical models of pancreatic, colorectal cancer and lung cancer, and several additional clinical trials evaluating CDK4/6 inhibitors with either MEK or ERK inhibitors are ongoing (NCT02022982, NCT02703571)." (PMID 30167080, 2018). "With 269 novel interactions, OncoPPi greatly expands the landscape of interactions among this selected set of lung cancer genes and defines interactions with potential significance for cancer PPI target discovery, such as CDK4/STK11, LATS2/RASSF1 and MYC/NSD3 (WHSC1L1)." (PMID 28205554, 2017). "One of them codes for the cyclin‐dependent kinase 4, a member of the Ser/Thr protein kinase family that is important for cell cycle G1–S transition by the RB1–CCND1–CDKN2A pathway that is known to be damaged in lung cancer." (PMID 27632354, 2017). "To further verify the role of NDUFA4 in the growth and metastasis of lung cancer cells, we detected the expression of cell-growth-related molecules including CDK2, CDK3, CDK4, and CDK6, as well as metastasis-related molecules including CXCR4, E-Cadherin, MMP2, MMP3, and MMP9, respectively." (PMID 28325285, 2017). "Despite overall inhibition of CDK4/6 has not been shown to be effective in lung cancer, it is possible the subset of patients with a SMARCA4 mutation may be more sensitive to CDK4/6 inhibitors." (PMID 37345003, 2023). "Thus, these clinical trials suggest that monotherapies targeting CDK4/6 are not very effective treatment for lung cancer patients, and CDK4/6 inhibitors combining with other drugs rank as a reasonable strategy." (PMID 35814226, 2022). "Since CDK4/6 inhibitors inevitably develop drug resistance, and monotherapy with CDK4/6 inhibitors, including abemaciclib is not very effective for the treatment of lung cancer patients, drug combination is thus a reasonable therapeutic strategy." (PMID 35814226, 2022). "Indeed, treatment with a CDK inhibitor appears to synergize well with checkpoint blockade therapy, as CDK4/6 inhibitors have been shown to significantly enhance T cell activation and augment the response to PD1 blockade in preclinical models of breast and lung cancers." (PMID 34771508, 2021).
lung cancer (continued). "With the recent development of highly specific CDK4/6 inhibitors (Palbociclib, Ribociclib, and Abemaciclib) and the approval of their use by the FDA for advanced metastatic breast cancer, designing multiple clinical trials using these agents for lung cancer have attracted great interest." (PMID 34395246, 2021). "IRF1 is downregulated in lung cancer, IPF and PAH datasets, probably because it represses the expression of genes involved in anti-proliferative response, such as BIRC5/survivin, CCNB1, CCNE1, CDK1, CDK2 and CDK4 and in immune response, such as FOXP3, IL4, ANXA2 and TLR4." (PMID 31867044, 2019). "Indeed, with our focused set of 83 lung cancer genes, we identify >260 novel interactions, expanding the PPI landscape for this gene set by >200%, including for well-studied cancer genes like MYC and CDK4." (PMID 28205554, 2017). "However, contrary to previous studies indicating that the combination of MAPK and CDK4/6 inhibitors induces RB protein-mediated cellular senescence and SASP activation, thereby enhancing NK cell immune surveillance and leading to the death of KRAS-mutant lung cancer cells." (PMID 40181456, 2025). "In addition, quizartinib is an another selective FLT3 (target of gilteritinib) inhibitor that is also effective to combine with abemaciclib to inhibit proliferation of lung cancer cells, suggesting that FLT3 might confer synthetic lethality to CDK4/6 inhibition." (PMID 35814226, 2022). "However, we observed that the expression level of CDK4 was positively correlated with the status of pathology classification(P = 0.047) lymph node metastasis (N classification) (N0-N1 vs. N2-N3) (P = 0.007), and clinical stage (I-II vs. III-IV) (P = 0.004) in lung cancer patients." (PMID 21477379, 2011). "CDK4/cyclin D kinase constitutes an attractive pharmacological target for development of anticancer therapeutics, in particular in KRAS-mutant lung cancer patients, who have a poor prognosis and no targeted therapy available yet." (PMID 32104498, 2020).
glioma (174 papers, 2006 to 2026). A benign or malignant brain and spinal cord tumor that arises from glial cells (astrocytes, oligodendrocytes, ependymal cells). "In particular, EGFR (22/26) and CDK4 (6/8) mutations were more present in patients with GBM than those with other gliomas, whereas PDGFRA CNVs were present only in patients with GBM (3/3; data not shown)." (PMID 36959606, 2023). "Nevertheless, as CDKN2A loss shapes glioma cells into a higher-grade phenotype, it subsequently interacts with CDK4/6 expression in those tumors." (PMID 36831610, 2023). "Unrestricted cell cycle progression and rapid growth caused by abnormal CDK4/6 signaling have been confirmed as glioma progression markers." (PMID 37139163, 2023). "For example, gliomas with deletion or mutation of Rb are naturally insensitive to CDK4/6 inhibitors, but the wild-type Rb cancers would overexpress the Rb protein to gradually promote resistance to palbociclib." (PMID 35785151, 2022). "Our data showed that silencing BYSL caused cell cycle arrest at G1 phase in glioma cells, which was further verified by the downregulation of cyclin D1 and CDKs (CDK4 and CDK6) and the upregulation of CDKIs (P21 and P27)." (PMID 33628587, 2021). "According to preclinical data, CDKN2A deficiency sensitizes IDH-mutant glioma to CDK4/6 inhibitors." (PMID 41546701, 2026). "In contrast, while 5/6 NF1-associated gliomas epigenetically aligning with IDH-wildtype glioblastoma harbored either CDKN2A homozygous deletion or CDK4 amplification similar to NF1-associated HGAP, only one of these six tumors had ATRX mutation, and none exhibited piloid features." (PMID 35945463, 2022). "miR-7 abundance in glioma tissues was negatively associated with CDK4 mRNA level." (PMID 34719318, 2021). "Concurrently, CDK4/6 overexpression reduces drug efficacy, as shown in CDK4-amplified alveolar rhabdomyosarcoma and glioma models, while CDK6 upregulation in resistant MCF-7 cells restores Rb phosphorylation capacity." (PMID 40421216, 2025). "In high-risk gliomas, recurrent CNVs—such as chromosome 7/12 amplifications (EGFR, CDK4/MDM2) and chromosome 1/8/13 deletions (CHD5, DLC1, RB1)—play pivotal roles in promoting proliferation, immune evasion, and DNA repair defects." (PMID 40636690, 2025). "Additional preclinical studies are also warranted to explore potential therapeutic combinations utilizing CDK4/6 inhibition alongside other therapies in IDH-mutant glioma." (PMID 39944054, 2025). "Whilst several small sample clinical studies have indicated that the use of CDK4/6 inhibitors were well tolerated in adult and paediatric high-grade glioma, to the best of our knowledge, the combination with radiotherapy has not been explored clinically." (PMID 38212807, 2024). "CDCA3 is closely associated with many classic glioma biomarkers (CDK4, CDK6), and inhibitors of CDK4 and CDK6 have been shown to be effective in tumor therapy." (PMID 38728485, 2024). "The expression of cell cycle‐related proteins was downregulated obviously after glioma cells being incubated with T+A@Glu‐NPs for 48h, including cyclin D1 and CDK4." (PMID 39544152, 2024). "Previous studies have demonstrated that CDK4 and cyclin D1 are both key modulators promoting the G1 transition in glioma cells." (PMID 37545464, 2024). "Its predicted target genes include four hub genes, CCND1, SP1, CDK6 and CDK4, which are directly or indirectly involved in glioma development." (PMID 39348350, 2024). "CDK4 overexpression seems to be an enhancer of in vitro glioma colony formation, pushing glioma cell proliferation and extending their resistance to the temozolomide commonly used in HGGs." (PMID 36831610, 2023). "Palbociclib, an oral inhibitor of CDK4/6, has also been pre-clinically identified as an effective option for glioma." (PMID 37818357, 2023). "Upregulation of NAP1L1 increased its binding with c-Myc and activated c-Myc, which induced the expression of CCND1/CDK4, promoting glioma cell temozolomide resistance and proliferation." (PMID 37770914, 2023).
glioma (continued). "As the CDK4/6 pathway is highly dysregulated in glioma, the CDK4/6 inhibitor is considered an attractive novel therapeutic target for the treatment of glioma." (PMID 37896189, 2023). "The upregulation of NAP1L1 increased its binding with c-Myc and, further, activated c-Myc, which induced the expression of CCND1/CDK4 and thereby promoted the resistance to temozolomide and proliferation of glioma cells." (PMID 37770914, 2023). "Altogether, these results demonstrated that c-Myc regulated by NAP1L1 promoted glioma cell proliferation by inducing CCND1/CDK4." (PMID 37770914, 2023). "The gene expression analysis confirmed their over-expression in PBZ, similarly to what happens in low-grade glioma and glioblastoma, and CDK4 high levels seem to negatively influence patient overall survival." (PMID 36769158, 2023). "We also observed regional heterogeneity in genes associated with poor clinical prognosis in IDH-mutant glioma, including CDKN2A/B, CDK4, MYC, MYCN, and PDGFRA23." (PMID 37770427, 2023). "The upregulation of NAP1L1 increased its binding with c-Myc and thereby activated c-Myc, inducing the expression of CCND1/CDK4 and thereby promoting glioma cell temozolomide resistance and proliferation." (PMID 37770914, 2023). "The GISTIC 2.0 assessment uncovered numerous remarkable amplified regions containing multiple oncogenes in glioma patients with higher risk scores, consisting of 1q32.1 (PIK3C2B), 12q14·1(CDK4), 7p11·2 (EGFR), and 4q12 (PDGFRA)." (PMID 36311792, 2022). "CDK4 is also amplified or overexpressed in a variety of tumor types, including sarcomas, gliomas, lymphomas and those of the breast [reviewed in 1]." (PMID 36051751, 2022). "Genes associated with the neuronal differentiation pathway (Pcsk9, Runx1, Cebpb, Fzd4, Wnt7a, Ascl1, Fzd2, Edn3, Olig2, and Gpc2), gliomas (Shc1, Cdk4, E2f2, and Ccnd1), and cell cycle (Bub1b, Bub, Ccnb1, Ccnb2, and Cdc20) were significantly downregulated." (PMID 36147849, 2022). "Deregulation of cyclin‐dependent kinase 4/6 (CDK4/6) is detected in various types of cancers, including glioma." (PMID 35785151, 2022). "Specifically, high levels of CDK4 were observed in glioma tissues, and the inhibitors of CDK4/6 block cell proliferation, induced apoptosis, and enhanced the cell sensitivity to temozolomide in glioma patients." (PMID 36419652, 2022). "On the other hand, high-grade gliomas exhibit altered expression of any of the p16INK4a, cyclin-dependent kinase 4 (CDK4), or retinoblastoma 1 (RB1) genes, resulting in the loss of normal RB1 function." (PMID 35922753, 2022). "Six of those genes were found in three of the six most enriched ‘glioma TADs’: 2160 (CDK4, TSFM, TSPAN31, B4GALNT1), 2337 (NFATC4) and 2688 (CACNA1G)." (PMID 34341417, 2021). "Then, Western blot analysis was performed to investigate the effect of curcumin on cyclin D1, CDK4/6, Bcl‐2 and Bcl‐XL in glioma cells." (PMID 34169637, 2021). "The purposes of our research were to explore the role of Sev in glioma cell viability, invasion, and colony formation ability, and analyze the interaction between Sev and the HMMR-AS1/miR-7/CDK4 axis in glioma cells." (PMID 34719318, 2021). "The forest map of Cox regression analysis indicated that SMC3 and GADD45G were positively correlated with the prognosis of patients with glioma, whereas CDK4, WEE1, and HMGB2 were negatively correlated with prognosis." (PMID 34123852, 2021). "This study is the first to identify that Sev can play the anti-glioma role via regulating HMMR-AS1/miR-7/CDK4 axis." (PMID 34719318, 2021). "miR-7 overexpression inhibited cell viability, invasion, and colony formation ability via reducing CDK4 in glioma cells." (PMID 34719318, 2021).